EDNRB (endothelin receptor type B)
Description:
Non-specific receptor for endothelin 1, 2, and 3. Mediates its action by association with G proteins that activate a phosphatidylinositol-calcium second messenger system.
Synonyms: ET-B; ET-BR; ETRB; ETB; ABCDS; ETB1; ETBR; HSCR; HSCR2; WS4A
Tractability: Small molecule: an approved drug acts on it; a structure with a bound ligand is known; a high-quality ligand is known; it belongs to a druggable protein family. Antibody: UniProt places it where antibodies can reach, with high confidence; its Gene Ontology location is reachable by antibodies, with high confidence; UniProt predicts a signal peptide or a membrane-spanning region; the Human Protein Atlas places it where antibodies can reach. PROTAC: its protein half-life has been measured; a small molecule that binds it is known. Other modalities: a drug acting on it is in phase 1 trials.
Target class: Family A G protein-coupled receptor; Short peptide receptor (family A GPCR); Membrane receptor; Peptide receptor (family A GPCR); Endothelin receptor
Chemical probes: A-192621 (high quality), CHEMBL413825, PD083435
Safety:
Unwanted effects reported when the protein is acted on. In parentheses: how it was acted on, where the effect was seen, and who reports it.
bronchoconstriction (activation, acute dosing; respiratory, renal, cardiovascular, gastrointestinal, blood; source: Lynch et al. (2017))
cardiovascular malformations (inhibition, developmental toxicity; respiratory, renal, cardiovascular, gastrointestinal, blood; source: Lynch et al. (2017))
cell proliferation (activation, acute dosing; respiratory, renal, cardiovascular, gastrointestinal, blood; source: Lynch et al. (2017))
craniofacial abnormalities (inhibition, developmental toxicity; respiratory, renal, cardiovascular, gastrointestinal, blood; source: Lynch et al. (2017))
decreased gastric emptying (inhibition, acute dosing; respiratory, renal, cardiovascular, gastrointestinal, blood; source: Lynch et al. (2017))
decreased intestinal transit (inhibition, acute dosing; respiratory, renal, cardiovascular, gastrointestinal, blood; source: Lynch et al. (2017))
decreased pain (inhibition, acute dosing; respiratory, renal, cardiovascular, gastrointestinal, blood; source: Lynch et al. (2017))
decreased platelet aggregation (activation, acute dosing; respiratory, renal, cardiovascular, gastrointestinal, blood; source: Lynch et al. (2017))
decreased then increased blood pressure (activation, acute dosing; respiratory, renal, cardiovascular, gastrointestinal, blood; source: Lynch et al. (2017))
decreased urine excretion (inhibition, acute dosing; respiratory, renal, cardiovascular, gastrointestinal, blood; source: Lynch et al. (2017))
glomerular and tubulointerstitial structural injury (activation, acute dosing; respiratory, renal, cardiovascular, gastrointestinal, blood; source: Lynch et al. (2017))
increased blood pressure (inhibition, acute dosing; respiratory, renal, cardiovascular, gastrointestinal, blood; source: Lynch et al. (2017))
increased then decreased heart rate (activation, acute dosing; respiratory, renal, cardiovascular, gastrointestinal, blood; source: Lynch et al. (2017))
left ventricular hypertrophy (activation, acute dosing; respiratory, renal, cardiovascular, gastrointestinal, blood; source: Lynch et al. (2017))
pulmonary hypertension (activation, acute dosing; respiratory, renal, cardiovascular, gastrointestinal, blood; source: Lynch et al. (2017))
Gene: Protein-coding gene on chromosome 13 (77,895,481 to 77,975,529, reverse strand). Ensembl gene ENSG00000136160.
Subcellular location: Cell membrane
Subcellular location (Human Protein Atlas): Plasma membrane; Cytosol
Pathways (Reactome):
Signal Transduction: G alpha (q) signalling events; Peptide ligand-binding receptors
Developmental Biology: Transcriptional and post-translational regulation of MITF-M expression and activity
Gene Ontology:
Molecular function: endothelin receptor activity; peptide hormone binding; protein binding; G protein-coupled receptor activity; type 1 angiotensin receptor binding
Biological process: calcium-mediated signaling; endothelin receptor signaling pathway; macrophage chemotaxis; negative regulation of protein metabolic process; negative regulation of transcription by RNA polymerase II; vasoconstriction; vein smooth muscle contraction; cell surface receptor signaling pathway; developmental pigmentation; enteric nervous system development; enteric smooth muscle cell differentiation; negative regulation of adenylate cyclase activity; negative regulation of neuron maturation; nervous system development; phospholipase C-activating G protein-coupled receptor signaling pathway; aldosterone metabolic process; calcium ion transmembrane transport; canonical Wnt signaling pathway; cellular response to lipopolysaccharide; cGMP biosynthetic process; chordate pharynx development; epithelial fluid transport; G protein-coupled receptor signaling pathway; gene expression; melanocyte differentiation; and 20 more
Cellular component: plasma membrane; membrane; nuclear membrane
Genetic constraint (gnomAD): Loss-of-function variants: 18 observed, 45.59 expected, observed/expected ratio (o/e) 0.39, 90% interval 0.27 to 0.58. The upper end of that interval is the gene's LOEUF score, 0.58, which puts it in group 2 of 6, group 1 being the genes least tolerant of losing a copy. Missense variants: 434 observed, 555.95 expected, observed/expected ratio (o/e) 0.78, 90% interval 0.72 to 0.85. Synonymous variants: 213 observed, 210.51 expected, observed/expected ratio (o/e) 1.01, 90% interval 0.9 to 1.13.
Gene-disease validity (ClinGen):
ClinGen rates the evidence that EDNRB causes each of these diseases.
Waardenburg syndrome type 4A (autosomal recessive): Moderate.
Waardenburg syndrome type 4A (autosomal dominant): Limited.
Homologues: Orthologues: chimpanzee EDNRB (100% identical), macaque EDNRB (98% identical), rabbit EDNRB (91% identical), pig EDNRB (90% identical), mouse Ednrb (89% identical), rat Ednrb (89% identical), dog EDNRB (86% identical), guinea pig EDNRB (80% identical), zebrafish ednrba (64% identical), tropical clawed frog ednrb (50% identical), zebrafish ednrbb (50% identical). Paralogues in human: EDNRA (52% identical), GRPR (25% identical), NMBR (25% identical), BRS3 (24% identical), GPR37 (24% identical), GPR37L1 (23% identical), NMUR1 (19% identical), NTSR1 (19% identical), TRHR (18% identical), NMUR2 (18% identical), GHSR (17% identical), MLNR (17% identical), and 3 more.
Diseases named in the same sentence as EDNRB in open-access papers:
EDNRB is named in the same sentence as 201 diseases in open-access papers, as found by Europe PMC text mining. Sharing a sentence is not in itself a finding about the gene and the disease. The quoted sentences say what the papers report.
melanoma (42 papers, 2002 to 2025). A malignant, usually aggressive tumor composed of atypical, neoplastic melanocytes. "Another GPCR, endothelin receptor type B (EDNRB), a target for endothelins, plays an important role in melanocyte development and differentiation, but has also been associated with melanoma progression." (PMID 38927967, 2024). "Levels of miR-31-5p were inversely associated with expression of its target MEL gene EDNRB, known to play an essential role in normal melanocyte development as well as melanoma proliferation, metastatic initiation, and BRAF inhibitor resistance." (PMID 35810190, 2022). "The up-regulation of EDNRB was associated with aggressive melanoma, and EDNRB was suggested to be a potential tumor progression biomarker in melanoma." (PMID 30020984, 2018). "Among the down-regulated genes, we found MITF which controls proliferation and invasiveness of melanoma cells and the endothelin receptor b (EDNRB) which is strongly associated with melanoma development and central nervous system directed metastasis." (PMID 24799129, 2014). "EDNRB, a receptor of the endothelin signaling pathway, is essential for the development of neural crest melanocytes and is associated with the progression of melanoma." (PMID 34722301, 2021). "Variants in EDNRB have been loosely associated with increased melanoma risk in humans and are hypothesized to play a role in CNS melanoma metastases." (PMID 25679399, 2015). "EDNRB is greatly enhanced during the transformation of normal melanocytes to melanoma cells where it is thought to play a role in the associated loss of differentiation seen in melanoma cells." (PMID 18837980, 2008). "We constructed plasmids for both wild and mutant Endothelin Receptor Type B, as well as Endothelin-1, and transfected them into mouse melanoma cells." (PMID 40002960, 2025). "This trial evaluated the EDNRB antagonist BQ-788 in melanoma but was terminated due to patient recruitment challenges." (PMID 40597436, 2025). "Inactivation of EDNRB has been identified as a pivotal factor in the development of certain cancer types, including melanoma and gastric cancer." (PMID 38205153, 2024). "A further piece of supporting evidence is found in a mouse model of melanoma, where PlxnC1 expression was positively correlated with Ednrb, suggesting a role in the Ednrb/EDNRB-mediated suppressive effect on melanoma development." (PMID 39001376, 2024). "In this model, ET is secreted by melanoma cells and activates EDNRB in an autocrine and/or paracrine manner." (PMID 35158973, 2022). "Melanoma is a skin ageing phenotype; EDNRB is downregulated in melanoma skin relative to adjacent normal skin (GSE44805, Expression Ratio = 0.56, p-Value = 6.94E−03)." (PMID 35907981, 2022). "Of the eight GPCRs shown to be involved in pigmentation, only three have been studied in the context of melanoma (EDNRB, MC1R, and GRM1)." (PMID 35158973, 2022). "For example, activation of EDNRB by ET-1 secreted by surrounding melanoma cells induces reactivation of the MAPK pathway after BRAFi treatment." (PMID 35158973, 2022). "The EDNRB is the predominant receptor expressed by melanocytes/melanomas and binds all ETs with the same affinity." (PMID 35158973, 2022). "EDNRB was found to be upregulated in melanoma metastasis and altered tumor–host interactions leading to melanoma progression." (PMID 34722301, 2021). "They conjugated iron-carrying CPNPs with the endothelin 3 (EDN3-CPNP), which specifically targets the melanoma endothelin-B receptor (EDNRB), and showed enhanced melanoma tumor targeting and tumor cell killing effects." (PMID 34796174, 2021). "A strong induction of EDNRB has been described in a subgroup of melanoma patients, and EDNRB expression has been found to correlate with melanoma malignancy." (PMID 31464372, 2019). "In conclusion, the signalling model proved a successful tool to identify kinases through which the EDNRB signalling network controls melanoma cell migration." (PMID 31464372, 2019).
melanoma (continued). "EDNRB signalling in melanoma cells was chosen, as it has a defined role in the development and homeostasis of this cell type and its dysregulation has been implicated in melanoma pathogenesis (Saldana‐Caboverde & Kos, 2010)." (PMID 31464372, 2019). "For instance, in skin cutaneous melanoma (SKCM), ADGRG1/GPR56, GPR143, and EDNRB are highly overexpressed and highly expressed in magnitude compared to normal skin in >90% of melanoma samples." (PMID 31765370, 2019). "Pharmacological inhibition of kinases identified by the model as central nodes of the EDNRB network was used to test their role in EDN‐induced melanoma cell migration." (PMID 31464372, 2019). "Functional studies have shown that EDNRB inhibition leads to melanoma cell death in culture and reduces melanoma growth in mice through induction of apoptosis." (PMID 31464372, 2019). "We investigated phosphoproteomic changes caused by endothelin B receptor (ENDRB) activation in the melanoma cell lines UACC257 and A2058 and built an integrated model of EDNRB signalling from the phosphoproteomics data." (PMID 31464372, 2019). "In line with our previous findings that MITF is up‐regulated on treatment, we found that EDN1 as well as EDNRB expression increased in melanomas of patients (n = 22) on treatment." (PMID 28606996, 2017). "EDN1 signals through endothelin receptors, of which EDNRB is essential for melanocyte development (Saldana‐Caboverde & Kos, 2010), and its expression is highly enriched in melanoma cells (Fig EV4D)." (PMID 28606996, 2017). "In general, EDNRB expression is positively correlated with melanoma progression in cutaneous melanoma." (PMID 27148356, 2016). "SOX10 is known to act as a specifier of neural crest derivatives and directly regulates melanoma associated genes like ERBB3, EDNRB and MITF." (PMID 24799129, 2014). "Hypermethylation of EDNRB gene promoter has been observed in leukemia, oral cancer, skin cancer, head and neck cancer, melanoma, renal cell carcinoma, bladder cancer and prostate cancer." (PMID 24326135, 2013). "Among the genes found to be downregulated in the UVM subtracted library, several were previously associated with melanoma, such as melanocytic markers TYRP1, EDNRB, MTAP, and sex determining region Y box 4 (SOX4)." (PMID 21647268, 2011). "KIT, a receptor tyrosine kinase, and EDNRB, a G-protein coupled receptor, are critical regulators in melanocyte development and pigmentation signalling, hair and skin development, and melanoma progression." (PMID 21294715, 2011). "Validation studies reveal that these genes impact pigment production and EDNRB signaling in pigmented melanoma cells (MNT-1) and normal melanocytes." (PMID 20550706, 2010). "EDNRB has been extensively studied in several cancers, including breast cancer and melanoma." (PMID 40597436, 2025). "We added ET-3 because it is the ETB-specific ET and no ETA-binding activity was found in the melanoma microenvironment associated with EDNRB overexpression (see dataset a1, a2 in SI)." (PMID 39833448, 2025). "It would be of great interest to generate a mouse model that reflects the human EdnRB situation in cutaneous melanoma: overexpression of EDNRB (human and mouse) in melanocytes/melanoma combined with oncogenic BRAFV600E or NRASQ61K/R, the major driver mutations in human cutaneous melanoma." (PMID 35158973, 2022). "Using the PHONEMeS approach, all linear paths linking EDNRB to the target sites identified by the phosphoproteomic analysis in the melanoma cells were collected and an optimised solution combining these paths into a network was calculated using Integer Linear Programming." (PMID 31464372, 2019). "In addition to its autocrine effect, melanoma cell‐derived EDN can activate EDNRB on endothelial cells to induce angiogenesis and neovascularisation in a different mouse model." (PMID 31464372, 2019).
melanoma (continued). "The four kinases identified could be candidate drug targets for combination therapy with EDNRB inhibitors to treat melanoma progression by reducing melanoma cell spreading and metastatic potential." (PMID 31464372, 2019). "In order to test whether therapeutic intervention with EDNRB signalling represents a relevant strategy for melanoma patients, we analysed melanoma samples isolated from patients when they had been on treatment for 2 weeks." (PMID 28606996, 2017). "Indeed, EDNRB depletion through RNAi prevented EDN1 from protecting melanoma cells from BRAF inhibition." (PMID 28606996, 2017). "Endothelin receptor B (EDNRB), a G protein-coupled receptor that is upregulated in melanoma metastases, is another molecule that could enable the preferential colonization of the brain by melanoma." (PMID 27598148, 2016). "Interestingly, Bambi is co-expressed with a well-known melanoma-associated gene, EDNRB, important for angiogenesis suggesting that BAMBI is a part of a network of genes regulating vascular growth in melanoma." (PMID 27689402, 2016). "When compared to other types of skin cancer such as basal cell carcinoma or squamous cell carcinoma, BAMBI showed selective overexpression in melanoma and strong co-expression (0.815) with the established melanoma gene EDNRB, but also with HEY1 (0.759), a gene important for vascular development." (PMID 27689402, 2016). "Additionally, if EDNRB is heterozygously deleted in a mouse transgenically expressing RET—another Hirschsprung disease gene—mice develop de novo melanoma lesions." (PMID 25679399, 2015). "EDNRB gene silencing by promoter hypermethylation has been reported in a variety of tumors such as leukemia, oral cancer, skin cancer, head and neck cancer, melanoma, renal cell carcinoma, bladder cancer, and prostate cancer." (PMID 24326135, 2013). "This suggests that EDNRB could be a potential therapeutic target for melanoma." (PMID 36341437, 2022). "However, in contrast to what we observed in A375 cells, A375‐T cells were not able to protect A375‐shEDNRB cells from BRAF inhibition, indicating that EDNRB‐mediated signalling plays an important role in paracrine protection to MAPK pathway inhibition in melanoma cells." (PMID 28606996, 2017). "We constructed recombinant plasmid for wild and mutant EDNRB and EDN1, respectively, and transfected the recombinant plasmid into mouse B16 melanoma cells in groups." (PMID 40002960, 2025). "Module M3 contained JUND, SOX2, THAP11, and JUN, as well as regulators for C5 Melanoma MAGEA4, C6 Melanoma GJB2, C2 melanoma EDNRB, and C1 melanoma CDH19." (PMID 37435067, 2023). "Small-molecule inhibitors of EDNRB, A-192621 and BQ788, were shown to inhibit the growth and survival of melanoma cells in culture and in xenografts." (PMID 35158973, 2022). "In melanoma-related studies, the prognostic value of patients with high CD8(+) T cell subpopulations expressing EDNRB was significantly reduced." (PMID 36341437, 2022). "EDNRB, which is highly overexpressed in SKCM, promotes migration and transformation of melanocytes and melanoma cells, and inhibition of EDNRB is pro-apoptotic." (PMID 31765370, 2019). "A similar situation was observed in melanomas from patients, where EDNRA expression levels were also lower than EDNRB levels and were increased on treatment." (PMID 28606996, 2017). "Among 142 upregulated genes in melanoma, many are known to be expressed specifically in melanocytes, including KIT, Melan-A, TYR, TRPM1, EDNRB, DCT, SOX10 and SILV." (PMID 21294715, 2011). "Moreover, the expression of TYR, MITF, EDNRB, and TRP-1/2 was elevated again when rosiglitazone and GW acted together on melanoma cells, as PPAR-γ was activated." (PMID 38159176, 2024).
melanoma (continued). "These genes along with their activation values Eq for melanoma (MEL) are, GPNMB (MEL activation = 18.59), UBL3 (MEL activation = 1.39), AP1S2 (MEL activation = 1.28), RAB38 (MEL activation = 0.91), EDNRB (MEL activation = 0.55), JUN (MEL activation = 0.34), and C1orf21 (MEL activation = -0.13)." (PMID 34570764, 2021). "We could further confirm the mutual exclusion of MITF/EDNRB and AXL/EDNRA expression in a panel of melanoma cell lines." (PMID 28606996, 2017). "In contrast to these studies, putative loss-of-function germline variants in EDNRB were associated with cyclin-dependent kinase inhibitor 2A, CDKN2A, variants in familial melanoma cases in a French population, but not in an Italian population." (PMID 27148356, 2016). "In addition, other genes known to be expressed in melanocytes, including MLANA, SILV, EDNRB and melanophilin, were also detected in these EGIR specimens overlying melanoma." (PMID 21294715, 2011). "Thus, the neural crest origin, but de‐differentiated nature of AXL‐high melanoma cells might explain why they express preferentially EDNRA, while differentiation towards the melanocyte lineage, triggered by MITF expression, results in a switch to EDNRB expression." (PMID 28606996, 2017).